TERT (telomerase reverse transcriptase)
Diseases named in the same sentence as TERT in open-access papers (continued):
Sharing a sentence is not in itself a finding about the gene and the disease.
cancer (continued). "Thus, we speculate that a fine interplay between TERT and KRAS signaling is critical to drive proper tissue renewal, and that balanced activation of those two is critical to avoid deleterious consequences such as cancer initiation." (PMID 35149726, 2022). "The mutant TERT had a tendency to be more frequent in downstaged vs. not downstaged (p = 0.074, statistically not significant), suggesting that in several of these cases, the downstaging may have led toward an underestimation of cancer aggressivity." (PMID 33562809, 2021). "Thus, telomerase/TERT contributes to several hallmarks of cancer which may be dependent or independent of its catalytic activity." (PMID 32674474, 2020). "However, when TERT was co-expressed with H-Ras, these cells became tumorigenic and this transformation was independent of the catalytic activity of TERT, suggesting that hTERT has additional roles in cancer promotion that are distinct from its activity at telomeres." (PMID 28264499, 2017). "Furthermore, the expression level of telomerase reverse transcriptase (TERT) and telomerase RNA component (TERC) transcripts, closely related with telomerase activity, was investigated by RT-PCR assay in the A-549, MDA-MB-231 and U87-MG cancer cells treated with 1 μM SMA." (PMID 30460075, 2017). "Given the number of miRNAs associated with TL, TERT rs2736118 and ALT genes, our data also support the hypothesis that telomere-related genes, in addition to affecting TL, impact non-TL-related functions that can importantly influence cancer risk." (PMID 27627813, 2016). "The fact that TERT not only interacts with and stabilizes β-catenin, but also is a direct target of β-catenin signaling, indicates that highly complex and interdependent regulatory networks mediate canonical and non-canonical telomerase activities in cancer cells." (PMID 24983628, 2014). "Cancer and reproductive disease add prominent non-MHC signals at TERT and CLPTM1L alongside pan-category genes such as MIS18BP1 and BIRC3." (PMID 41166152, 2026). "Among these, the TERT Hypermethylated Oncological Region (THOR) has emerged as a paradoxical regulatory hotspot: rather than repressing transcription, cancer-specific hypermethylation of THOR facilitates hTERT activation." (PMID 41375001, 2025). "These outcomes of TERT AS also matched our predictions that SRSF2 and U2AF2 were FL TERT promoters in cancer cells, while HNRNPM would not impact splicing of TERT exons 7/8." (PMID 37531400, 2023). "TERT (telomerase reverse transcriptase) mRNA and other non-coding RNAs carried by cancer-derived EVs may induce and stimulate telomerase expression in recipient fibroblasts and mutant cell clones, allowing for the development of a cancer stem cell phenotype with replicative immortality." (PMID 35159299, 2022). "The TERT–NF-κB p65 interaction increased a subset of NF-κB-dependent gene expressions such as IL-6 and TNF-α, which are critical for inflammation and cancer progression, suggesting a noncanonical role for TERT in cancer regulation." (PMID 35741087, 2022). "Lastly, a study of upstream TERT promoter methylation patterns in 312 PTC, FTC, MTC, and ATC patients found significantly higher upstream DNA methylation in patients with cancer recurrence than in patients whose tumors did not recur." (PMID 32849278, 2020). "While several studies reported successful utilization of TERT, survivin, and CXCR4 for transcriptional targeting in human cancers, none of these promoters have been investigated for their activity in canine tumors." (PMID 33166332, 2020). "For telomerase negative cancers, termed alternative lengthening of telomeres (ALT) cancers, TERC is often detected, but TERT is lacking." (PMID 31294790, 2019).
cancer (continued). "Contrary to our expectation, TERT and Survivin/BIRC5, which are highly expressed in various cancer cells, appeared not suitable as marker genes of immortalized RPE cells." (PMID 28811571, 2017). "Four post-treatment cancers also showed focal copy number gains of ERBB2, CCND2, TERT and CCNE1 that were absent from the pre-treatment samples." (PMID 27045317, 2016). "The ectopic expression of TERT via AAV-9 also did not lead to an earlier onset of cancer, thereby supporting the notion that ectopic expression of the genes that regulate telomeric maintenance does not necessarily induce cancer development." (PMID 39858038, 2025). "Here, we performed further analyses and characterization of HBV integrations identified by our recently reported VIcaller platform in recurrent or known HCC genes (such as TERT, MLL4, and CCNE1) as well as non-recurrent cancer-related genes (such as CSMD2, NKD2, and RHOU)." (PMID 33557409, 2021). "The TERT and EIF1AX gene locations were not included in the applied cancer panel." (PMID 29133385, 2018). "In contrast to TERT mRNA, telomerase RNA, TERC, is generally expressed ubiquitously, at times in the absence of telomerase activity, and thus it has been assumed that TERC would not be a suitable cancer marker." (PMID 27240403, 2016). "To test this hypothesis, we genotyped for two significant SNPs TERT-rs2736098 and CLPTM1L-rs4016981 in a case-control study with 501 cancer cases and 576 cancer-free controls in Chinese non-smoking population." (PMID 23738012, 2013). "TERT, MKI67, and MYC mRNA expression was higher in cancer tissues than in non-HCC liver samples." (PMID 22912812, 2012). "However, deepC-SV could not find any SE involved with three cancer-related genes (17.6%, 3/17): NFATC2 and SALL4 in MCF7, TERT in HCC1954." (PMID 39322849, 2024). "The experiments also demonstrated a co-occurrence of the activated TERT and DNA repair processes, and a co-activation of ALT and various oncogenic pathways, including E2F/DP1, MYC, YY1, ERK, NFκB, HIF1α and WNT, revealing that TERT inhibition alone is not enough to suppress cancer cells’ growth." (PMID 36615513, 2022).
CNS tumors (40 papers, 2016 to 2025). "TERT promoter mutations were detected in 31.6% of CNS tumor samples, consistent with previous reports." (PMID 40711866, 2025). "While these studies referred to mostly extra-meningeal SFTs, a large study from 2013 on TERT promoter mutations in 1515 CNS tumors found TERT promoter mutations in 50% (8/16) of meningeal SFTs." (PMID 38392213, 2024). "Future studies, particularly for the biphasic differentiation and the role of TERT promoter mutation were needed to clarify this unusual chromosomal rearrangement in the CNS tumor." (PMID 35912228, 2022). "Mutations of ATRX (or lack of protein expression) have been linked to the ALT mechanism, and mutations of the promoter of TERT result in upregulation of the telomerase, both events being mutually exclusive in CNS tumors." (PMID 32642724, 2020). "Because TERT promoter mutations are most common in CNS tumors, some authors hypothesize that meningeal SFTs have a higher prevalence of TERT promoter mutations than extra-meningeal SFTs." (PMID 38392213, 2024). "The relevance of TERT promoter mutations in this subset of CNS tumours needs further evaluation." (PMID 30183767, 2018). "Still, TERT promoter mutations are rare in pediatric tumors of the CNS." (PMID 27657132, 2016). "In Case 1, it is noteworthy that other hallmark characteristics of GBM, such as EGFR amplification, TERT promoter mutations, or gains of chromosome 7 with loss of chromosome 10, as well as other driver alterations in high-grade CNS neoplasms, were absent." (PMID 40575153, 2025). "For the mutation status of the TERT promoter, the group of GBM patients with non-CNS tumors consisted of a higher proportion of the status of TERT promoter mutation than the other group (68.40% TERT promoter mutation status in the former group compared to 47.00% in the latter group, p = 0.034)." (PMID 36575552, 2022). "A comprehensive analysis of the data reveals significant implications of the TERT-p status and MGMT methylation on distinct lobes, providing valuable insights into the molecular characteristics of CNS tumors." (PMID 38893240, 2024). "A meticulous examination of the data highlights the impact of the TERT-promoter status and MGMT methylation on the specific lobes, offering valuable insights into the molecular characteristics of CNS tumors." (PMID 38893240, 2024). "Other molecular characteristics of scGBM, including TERT promoter mutations, EGFR amplification, or combined gain of chromosome 7 and loss of chromosome 10 (+7/−10) mentioned in the 2021 WHO Classification of CNS Tumors, were not possible to examine." (PMID 40058218, 2025).
infection (40 papers, 2008 to 2025). The state of being infected such as from the introduction of a foreign agent such as serum, vaccine, antigenic substance or organism. "TERT expression and activity was significantly lower 4 days after infection with AD-TERT526mut-GFP in compared with AD-TERT-GFP infection, indicating that Chr13:73764526 hypomethylation is potentially implicated in abnormal expression of TERT." (PMID 36481932, 2023). "Infection of human primary T cells with HTLV1 has been shown to cause transcriptional activation of TERT gene." (PMID 36358677, 2022). "Stable genomic integration of the coding sequences of TERT (WT and the SNP variants) through infection with retrovirus vectors (pBabe-Hygro-flag3B-TERT) in BJ cells restored telomerase activity." (PMID 33619289, 2021). "Here, an increase in telomerase reverse transcriptase (TERT) protein expression is observed in chief cells upon infection with cagA‐positive H. pylori." (PMID 39587848, 2025). "The pan-p38 inhibitor Dora, neddylation inhibitor MLN4, and JNK inhibitor Jnk completely inhibited inflammasome assembly in HEKNLRP1+ASC and N/TERT-1C1C-EGFP cells after infection with SFV." (PMID 36315050, 2023). "Nearly all of the cells were infected with the respective viruses, but only SFV and SINV induced a robust assembly of ASC specks in HEKNLRP1+ASC and N/TERT-1C1C-EGFP cells 20 h after infection." (PMID 36315050, 2023). "Infection-induced mutual sequestration between miR-S1 and miR-1266 led to the derepressed expression of TERT and T antigens, which were involved in cellular transformation and viral replication." (PMID 36005825, 2022). "Lentiviral particles encoding rat telomerase reverse transcriptase (TERT) were obtained using pLV-PGK-TERT carrying synthetic TERT and further used to transduce hepatocytes at multiplicity of infection." (PMID 35804458, 2022). "To further examine the regulation between TERT and SLC7A11, we employed lentiviral infection to either overexpress or suppress TERT levels in MLE-12 cells." (PMID 34716298, 2021). "Upon infection with uropathogenic E. coli, metformin treated 5637 and TERT-NHUC cells showed upregulation in LL-37 at the mRNA and protein levels." (PMID 34584119, 2021). "We next tried to immortalize BJ fibroblasts by overexpression of TERT by lentiviral infection with pLOX-TERT-iresTK." (PMID 35127713, 2021). "The aim of this study was to assess telomerase activity, expression of TERT, cMyc, MMP-1, MMP-2, and MMP-9 in FOSCC cell lines associated with FcaPV-2 infection." (PMID 32292795, 2020). "Primary human hepatocytes and Huh-7.5 hepatoma cells showed early de novo TERT protein expression 2–4 days after infection and these events coincided with increased TERT promoter activation, TERT mRNA, and telomerase activity." (PMID 28056029, 2017). "TERT promoter was significantly activated early after infection and displayed a time course corresponding closely with the appearance of TERT mRNA and new protein." (PMID 28056029, 2017). "Collectively, our findings show that not only is TERT induced early in infection, but the systems responsible for TERT degradation are also activated, thus suggesting that the virus extensively influences the telomerase system." (PMID 28056029, 2017). "To build a global picture of changes in host and viral proteins throughout the course of MVA infection, we infected telomerase reverse transcriptase (TERT)-immortalised primary human foetal foreskin fibroblasts (HFFF-TERTs) with MVA at a multiplicity of infection (MOI) of 5 in biological duplicate." (PMID 38065956, 2023). "Similarly, the activity of a reporter containing TERT 3′ UTR (Luc-hTERT-3′ UTR) was enhanced by wtSV40 infection in miR-1266-expressing cells when compared to its infected control cells." (PMID 36005825, 2022). "However, wtSV40 infection conferred a similar TERT activity on control and miR-1266-expressing cells." (PMID 36005825, 2022).
infection (continued). "Similarly, RNase7 protein expression also increased in 5637 cells upon infection, though only mRNA upregulation was observed in TERT-NHUC." (PMID 34584119, 2021). "The results clearly show that the TERT infection resulted in the induction of enzyme activity." (PMID 33060611, 2020). "In addition, the treatment of cells with lycopene, an efficient singlet oxygen quencher, previously shown to prevent ROS production in H. pylori-infected cells, abolished the inhibitory effect of the infection on the TERT protein levels." (PMID 32082377, 2019). "However, SV40/TAD (a mutated strain lacking miR-S1 expression) infection conferred a similar level of LSTag and TERT on control and miR-1266-expressing cells, suggesting that miR-S1 expression induces an increase in LSTag and TERT in miR-1266-expressing cells." (PMID 36005825, 2022). "Moreover, immunoblotting analyses demonstrated that wtSV40 infection induced significantly increased protein expression of small T antigen in miR-1266-expressing cells, but had only marginal effects on the expression of large T antigen and TERT." (PMID 36005825, 2022). "Next, we sought to examine whether pre-binding PsV to ECM would similarly improve N/TERT infection." (PMID 32968082, 2020). "The upregulation of the Wnt target gene expression, including Axin2, EPHB2, CCND1, CD44, TERT, and MYC in PEDV-infected cells, further highlights the activation of WNT signaling in response to infection." (PMID 40396761, 2025). "To evaluate how vOka affects the upregulation of KRT15, we infected N/TERT keratinocytes with the pOka or vOka strains at equal levels of virus and monitored KRT15 levels post-infection." (PMID 39385182, 2024). "Inflammasome assembly after SFV infection was inhibited to similar extends in polyclonal knockouts of p38α and ASC in N/TERT-1C1C-EGFP cells." (PMID 36315050, 2023). "For example, N/TERT cells infected in KSFM with mCherry PsV showed low infection efficiency using SMI, however when used on N/TERT cells in F-media, efficiency increased from roughly 10% to nearly 80%." (PMID 32968082, 2020). "After infection both PHH and Huh-7.5 cells showed the appearance of lower molecular weight species of immunoreactive TERT of 37 and 45 kD." (PMID 28056029, 2017). "TERT shRNA was delivered into KrasG12D-overexpressing BEAS-2B and Calu-3 cells by lentivirus infection." (PMID 27329725, 2017). "Clearly, the interactions between TERT-2 cells and P. gingivalis are complex and up-regulation of CCR5 provides only a partial explanation for the increase in trans infection of R5-tropic HIV-1." (PMID 18371227, 2008). "The results showed an increase in the proportion of stem cells in the S and G2/M phases, upregulation of proliferation-related genes, and activation of the Wnt pathway, evidenced by the elevated expression of Wnt target genes such as AXIN2, EPHB2, CCND1, CD44, TERT, and MYC following infection." (PMID 40396761, 2025). "To further elucidate whether CagA‐induced SPEM was TERT‐dependent, we explored the effects of TERT depletion on the development of SPEM induced by H. pyloriWT infection." (PMID 39587848, 2025). "We established three TERT-immortalized rhesus macaque kidney cell lines with an intact IFN system, which might support infection by diverse viruses, including primate herpesviruses and ZIKV." (PMID 37146034, 2023). "Ectopic expression of TERT in human CD4+ and CD8+ T cells by retrovirus-mediated infection can induce high levels of telomerase activity and maintain telomere length, but no proliferation advantage was seen in TERT-transduced CD8+ cells." (PMID 38111043, 2023). "FBS containing media such as F-media, E-media and DMEM-FBS all stimulated N/TERT infection, but media lacking FBS (e.g. Optimem, DMEM) did not." (PMID 32968082, 2020). "Under our experimental conditions of infection, we verified that the decrease of TERT levels was not due to apoptosis." (PMID 32082377, 2019).
infection (continued). "Infection efficiency, as assessed by counting the number of IE1/IE2-positive cells at day three post-infection, was highest in MRC-5 cells, about two-fold lower in ARPE-19 cells, eight-fold lower in undifferentiated N/TERT-1 cells, and three-fold lower in differentiated N/TERT-1 cells." (PMID 30841507, 2019). "It is important to note the absence of TERT staining in the vicinity of the large aggregates of lymphocytes in the gastric mucosa and submucosa, at both 12 and 18 months of infection." (PMID 32082377, 2019). "After infection of primary human hepatocytes (PHH) or permissive Huh-7.5 cells with cell culture strain of HCV (HCVcc), there was increased TERT mRNA and protein expression as well as augmented TRAP activity that coincided with the rise of HCV RNA replication." (PMID 28056029, 2017). "Blocking the TERT-2 cell CCR5 receptor with antibodies significantly reduced trans infection of R5-HIV-1 (p < 0.001) but not X4-HIV-1 (not shown) to TZM-bl cells." (PMID 18371227, 2008). "TERT-immortalized primary human fetal foreskin fibroblasts (HFFF-TERTs) were infected with HCMV strain Merlin at a multiplicity of infection (MOI) of 10 for 48 h, with application of MG132 (or the equivalent amount of dimethyl sulfoxide (DMSO) as a control) for the final 12 h of infection." (PMID 32690704, 2020). "We tested HaCaT as well as N/TERT generated ECM, however both failed to promote N/TERT infection." (PMID 32968082, 2020). "PHH did not express detectable TERT nor telomerase activity until after infection." (PMID 28056029, 2017). "Duplication of the TERT gene and/or chromosomes that do not contain the provirus could lead to underestimation of the HIV DNA (infection frequency) as normalized to TERT or DNA mass." (PMID 31711503, 2019).